CCDC42 (coiled-coil domain containing 42)
Description:
Essential for male fertility. Required for sperm development.
Synonyms: CCDC42A; FLJ32734
Tractability: No criterion of Open Targets' tractability assessment is met for any kind of drug.
Gene: Protein-coding gene on chromosome 17 (8,729,930 to 8,745,970, reverse strand). Ensembl gene ENSG00000161973.
Subcellular location: Cytoplasm, perinuclear region; Cytoplasm, cytoskeleton; Cell projection, cilium, flagellum; Cytoplasm, cytoskeleton, microtubule organizing center, centrosome
Gene Ontology:
Molecular function: protein binding
Biological process: spermatid development
Cellular component: centrosome; manchette; perinuclear region of cytoplasm; sperm head-tail coupling apparatus; sperm principal piece; cytoskeleton; motile cilium
Genetic constraint (gnomAD): Loss-of-function variants: 37 observed, 39.83 expected, observed/expected ratio (o/e) 0.93, 90% interval 0.71 to 1.22. The upper end of that interval is the gene's LOEUF score, 1.22, which puts it in group 5 of 6, group 1 being the genes least tolerant of losing a copy. Missense variants: 360 observed, 413.92 expected, observed/expected ratio (o/e) 0.87, 90% interval 0.8 to 0.95. Synonymous variants: 131 observed, 161.15 expected, observed/expected ratio (o/e) 0.81, 90% interval 0.7 to 0.94.
Homologues: Orthologues: chimpanzee CCDC42 (99% identical), macaque CCDC42 (94% identical), pig CCDC42 (87% identical), mouse Ccdc42 (86% identical), rat Ccdc42 (85% identical), guinea pig CCDC42 (84% identical), dog CCDC42 (80% identical), rabbit CCDC42 (79% identical). Paralogues in human: CFAP73 (34% identical), CFAP100 (22% identical), CCDC38 (17% identical).
Diseases named in the same sentence as CCDC42 in open-access papers:
CCDC42 is named in the same sentence as 8 diseases in open-access papers, as found by Europe PMC text mining. Sharing a sentence is not in itself a finding about the gene and the disease. The quoted sentences say what the papers report.
male infertility (2 papers, 2019 to 2023). The inability of the male to effect fertilization of an ovum after a specified period of unprotected intercourse. "However, since the only obvious phenotype of CCDC42-deficient mice is male infertility, CCDC42 is either dispensable for the somatic centrosome or its function has been taken over by other members of the CFAP73 family." (PMID 31475146, 2019). "Knockout of Ccdc9, Ccdc38, Ccdc42, Ccdc62, Ccdc87 and Ccdc136 results in male infertility in mouse models because of defects in sperm flagella." (PMID 37601242, 2023).
Behcet disease (1 paper, 2016). A chronic, relapsing, multisystemic vasculitis characterized by mucocutaneous lesions, as well as articular, vascular, ocular and central nervous system manifestations. "A more intriguing functional relationship would be its involvement in immunological processes, as suggested by the association of CCDC42 with Behcet’s disease." (PMID 27936112, 2016). "A number of immunoregulatory pathways have implicated in Behcet’s disease; if CCDC42 belonged to any of these pathways, it might explain its role in both Behcet’s disease and heroin addiction, as heroin use is often associated with increased presence of infectious diseases." (PMID 27936112, 2016).
diabetes (1 paper, 2025). "These regions spanned genes (e.g., CCDC42, GYPE, MAP3K20, and OBI1) related to diseases (e.g., malaria infection and diabetes) with differing prevalence and incidence between populations." (PMID 41224710, 2025).
heroin addiction (1 paper, 2016). "Gene-based association analysis identified genome-wide significant association between variants in CCDC42 and heroin addiction." (PMID 27936112, 2016). "Analysis using the diagnostic criteria of heroin dependence yielded suggestive evidence for association between variants in the genes CCDC42 (coiled coil domain 42; p = 2.8x10-7) and BRSK2 (BR serine/threonine 2; p = 4.110−6)." (PMID 27936112, 2016).
Infertility (1 paper, 2019). "Ccdc42 is specifically expressed in testis and brain but deletion of Ccdc42 seems to affect exclusively male germ cells resulting in infertility." (PMID 31475146, 2019).
type 2 diabetes (1 paper, 2024). "The rs11658281 SNP is present in the CCDC42 (Coiled-coil domain-containing protein 42) gene and is related to sex hormones, type 2 diabetes, and vision disorders." (PMID 39457566, 2024).
CCDC42 also shares sentences with these, for which no sentence is quoted: infectious disease (1 paper); vision disorder (1).